LINC01977 (long independently transcribed non-coding RNA 1977)
Gene: Long non-coding RNA gene on chromosome 17 (79,805,999 to 79,827,704, forward strand). Ensembl gene ENSG00000262772.
Diseases named in the same sentence as LINC01977 in open-access papers:
LINC01977 is named in the same sentence as 6 diseases in open-access papers, as found by Europe PMC text mining. Sharing a sentence is not in itself a finding about the gene and the disease. The quoted sentences say what the papers report.
breast cancer (5 papers, 2021 to 2023). A primary or metastatic malignant neoplasm involving the breast. "In summary, LINC01977 was identified as a key oncogenic driver in breast cancer, and significantly promoted breast cancer cell proliferation, metastasis, and chemoresistance to DOX." (PMID 33869063, 2021). "Our data presented here suggested that LINC01977 was an attracting therapeutic target for breast cancer treatment." (PMID 33869063, 2021). "To continue to explore the biological function of LINC01977, we performed in vitro experiments using breast cancer cell lines, which further demonstrated that LINC01977 could promote breast cancer cell proliferation, metastasis, and resistance to DOX." (PMID 33869063, 2021). "Overall, LINC01977 may act as a novel prognostic indictor and potential therapeutic target for breast cancer patients." (PMID 33869063, 2021). "The LINC01977 is a novel carcinogenic promoter reported in breast cancer (BC)." (PMID 34594376, 2021). "Moreover, Linc01977 silencing in MDA-MB-231 and MCF-7 breast cancer cells impaired breast cancer cell growth and motility and also rendered cells more sensitive to the chemotherapeutic drug doxorubicin (DOX)." (PMID 36139687, 2022). "LINC01977 could facilitate breast cancer (BC) development and chemoresistance to doxorubicin." (PMID 36497407, 2022).
lung carcinoma (1 paper, 2021). "Notably, LINC01977 has not been studied in lung cancer, which suggests that we can do further investigation." (PMID 34594376, 2021).
tumor (4 papers, 2021 to 2023). "Consistently, tumor xenograft models uncovered that knockdown of Notch2 obviously inhibited LINC01977-induced tumor growth." (PMID 37198207, 2023). "Knockdown of LINC01977 delayed tumor growth, as reflected in tumor size, tumor weight, HE and Ki67 staining." (PMID 37198207, 2023). "The results indicated that overexpression of LINC01977 accelerated tumor growth, as revealed by bioluminescence imaging, tumor size and tumor weight." (PMID 37198207, 2023). "In the transwell assay, we observed increased tumor cell migration and invasion in the group with LINC01977 overexpression." (PMID 33869063, 2021). "Also, we evaluated the expression of LINC01977 in tumor tissues and normal tissues through the TCGA database and discovered that LINC01977 showed a high expression level in HCC tissues." (PMID 37198207, 2023). "Interestingly, our results revealed that SE-induced LINC01977 transcriptional activation was the specific intrinsic response to the adaptation of the tumor microenvironment with high-TAM2 infiltration in early-stage LUAD." (PMID 35982471, 2022). "Additionally, we assessed whether inhibition of LINC01977 affected tumor metastasis in the xenograft metastasis model." (PMID 35982471, 2022). "Subsequently, we performed qRT-PCR on 40 paired LUAD tissues and observed that LINC01977 was highly expressed in paired LUAD tumor tissues, which was validated in the other 186 unmatched LUAD tumor tissues and the GEO dataset of LUAD." (PMID 35982471, 2022). "Additionally, upon stimulation with TGF-β, increased LINC01977 expression was observed in LUAD cells (A427, H1299, SW1573, and H1975), but the changes were not significant in both tumor microenvironment-associated cells and human normal bronchial epithelium (HBE) cells." (PMID 35982471, 2022). "Furthermore, 3-D tumor sphere formation and 2-D plate clone formation were assessed to evaluate the clonogenicity of LUAD cells, and the results revealed that the absence of LINC01977 reduced the clonogenicity of LUAD cells." (PMID 35982471, 2022).
cancer (2 papers, 2022 to 2023). A tumor composed of atypical neoplastic, often pleomorphic cells that invade other tissues. "Analysis from Kyoto Encyclopedia of Genes and Genomes (KEGG) showed that highly expressed LINC01977 was associated with cancer, signal transduction, and transport and catabolism." (PMID 35982471, 2022). "We found that LINC01977, a cancer-testis lncRNA, was hijacked by SE, which promoted proliferation and invasion both in vitro and in vivo." (PMID 35982471, 2022). "Here, we identified a SE-lncRNA LINC01977, which is driven by corresponding SE, that was also identified to be a cancer-testis gene." (PMID 35982471, 2022). "LINC01977 is a cancer-testis gene obtained from the GTEx and TCGA databases." (PMID 37198207, 2023). "Herein, we identified a SE-lncRNA, LINC01977, also defined as a cancer-testis gene in LUAD." (PMID 35982471, 2022).
infection (1 paper, 2023). The state of being infected such as from the introduction of a foreign agent such as serum, vaccine, antigenic substance or organism. "HCC organoid models also confirmed that overexpression of LINC01977 by lentiviral infection promoted HCC organoid growth." (PMID 37198207, 2023).
LINC01977 also shares sentences with these, for which no sentence is quoted: lung adenocarcinoma (1 paper).